OSBPL5 (oxysterol binding protein like 5)
Description:
Lipid transporter involved in lipid countertransport between the endoplasmic reticulum and the plasma membrane: specifically exchanges phosphatidylserine with phosphatidylinositol 4-phosphate (PI4P), delivering phosphatidylserine to the plasma membrane in exchange for PI4P, which is degraded by the SAC1/SACM1L phosphatase in the endoplasmic reticulum. Binds phosphatidylserine and PI4P in a mutually exclusive manner. May cooperate with NPC1 to mediate the exit of cholesterol from endosomes/lysosomes. Binds 25-hydroxycholesterol and cholesterol.
Synonyms: KIAA1534; OBPH1; ORP5
Tractability: Antibody: UniProt predicts a signal peptide or a membrane-spanning region. PROTAC: ubiquitination databases record sites on it; its protein half-life has been measured.
Gene: Protein-coding gene on chromosome 11 (3,087,107 to 3,166,739, reverse strand). Ensembl gene ENSG00000021762.
Subcellular location: Endoplasmic reticulum membrane
Subcellular location (Human Protein Atlas): Vesicles
Pathways (Reactome):
Metabolism: Acyl chain remodelling of PS
Gene Ontology:
Molecular function: cholesterol binding; phosphatidylinositol-4-phosphate binding; phosphatidylserine binding; phosphatidylserine transfer activity; phosphatidylserine-phosphatidylinositol-4-phosphate exchange activity; oxysterol binding; phospholipid transfer activity; lipid binding
Biological process: intermembrane phospholipid transfer; phospholipid transport; cholesterol metabolic process; cholesterol transport; Golgi to plasma membrane transport; phosphatidylserine acyl-chain remodeling
Cellular component: endoplasmic reticulum membrane; endoplasmic reticulum-plasma membrane contact site; membrane; cytosol
Genetic constraint (gnomAD): Loss-of-function variants: 74 observed, 101.84 expected, observed/expected ratio (o/e) 0.73, 90% interval 0.6 to 0.88. The upper end of that interval is the gene's LOEUF score, 0.88, which puts it in group 3 of 6, group 1 being the genes least tolerant of losing a copy. Missense variants: 1,210 observed, 1,125.7 expected, observed/expected ratio (o/e) 1.07, 90% interval 1.02 to 1.13. Synonymous variants: 549 observed, 488.57 expected, observed/expected ratio (o/e) 1.12, 90% interval 1.05 to 1.21.
Homologues: Orthologues: macaque OSBPL5 (98% identical), chimpanzee OSBPL5 (91% identical), pig OSBPL5 (89% identical), dog OSBPL5 (89% identical), guinea pig OSBPL5 (87% identical), rat Osbpl5 (85% identical), mouse Osbpl5 (85% identical), zebrafish osbpl5 (60% identical), Drosophila melanogaster Orp8 (45% identical), Caenorhabditis elegans obr-3 (42% identical). Paralogues in human: OSBPL8 (56% identical), OSBPL10 (20% identical), OSBPL6 (20% identical), OSBPL11 (19% identical), OSBPL1A (19% identical), OSBPL9 (18% identical), OSBP2 (18% identical), OSBPL3 (18% identical), OSBP (17% identical), OSBPL7 (17% identical), OSBPL2 (13% identical).
Diseases named in the same sentence as OSBPL5 in open-access papers:
OSBPL5 is named in the same sentence as 30 diseases in open-access papers, as found by Europe PMC text mining. Sharing a sentence is not in itself a finding about the gene and the disease. The quoted sentences say what the papers report.
lung cancer (5 papers, 2019 to 2021). A malignant neoplasm involving the lung. "Nagano and colleagues reported that OSBPL5 are involved in the metastatic potential of lung cancer." (PMID 35284334, 2021). "Therefore, OSBPL5 and CALU play a role in lymph node metastasis by enhancing the invasiveness of lung cancer cells." (PMID 33504115, 2021). "Analysis of human lung cancer patients indicated a higher level of CALU and Oxysterol binding protein-like 5 (OSBPL5) in metastatic cancer cells than non-metastatic samples." (PMID 32469983, 2020).
joint disease (2 papers, 2019 to 2021). "Changes in the methylation levels of genes associated with skin/joint disease (MBP, OSBPL5, SNORD115, and HCG26) and joint disease (IL22, ELF5, PPP2R2D, PTPRN2, and HCG26) were found." (PMID 33869291, 2021). "Biological inference prioritized notable DMRs associated with skin disease (SIGLEC14, JAM3, PCOLCE, RXRB), skin and/or joint disease (MBP, OSBPL5, SNORD115, HCG26), and joint disease (IL22, ELF5, PPP2R2D, PTPRN2, HCG26)." (PMID 30779748, 2019). "Although few DMRs exceeded a 10% change in methylation, it is noteworthy that many of those which did play roles in the pathogenesis of skin disease (SIGLEC14, JAM3, PCOLCE, RXRB, ELF5, IL22), joint disease (MBP, HCG26, IL22, PPP2R2D, PTPRN2) or are known to be imprinted (OSBPL5, SNORD115)." (PMID 30779748, 2019).
atherosclerosis (1 paper, 2025). A disease characterized by the build-up of fatty material and calcium deposition in the arterial wall resulting in partial or complete occlusion of the arterial lumen. "OSBPL5 depletion promoted cholesterol accumulation in LEs/LYs and subsequently induced foam cell formation and atherosclerosis development." (PMID 40176913, 2025). "Taken together, the downstream genes of ARL4C, including ABCA1, ALDH1A3, ARF6, ENHO, FLNA, LRP6, OSBPL5, Snail2, and SOX2 play an important role in atherosclerosis." (PMID 40176913, 2025).
Cirrhosis (1 paper, 2023). A chronic disorder of the liver in which liver tissue becomes scarred and is partially replaced by regenerative nodules and fibrotic tissue resulting in loss of liver function. "Therefore, we hypothesized that hsa-miR-7-5p is involved in the regulation of cholesterol metabolism through OSBPL5 to influence the development of cirrhosis, which is a new research point." (PMID 37461343, 2023). "Therefore, we hypothesized that in cirrhosis, hsa-miR-7-5p targets OSBPL5 to regulate cholesterol metabolism, which affects downstream metabolite changes." (PMID 37461343, 2023).
cyst (1 paper, 2021). A sac-like closed membranous structure that may be empty or contain fluid or amorphous material. "Therefore, coexpression of OSBPL5/8 with the upregulated lncRNA DN20924 probably promoted an increase in the intracellular Ca2+ concentration as well as Ca2+ signaling pathway activation and consequently stimulated cyst formation." (PMID 33859278, 2021).
insulinoma (1 paper, 2020). "Conversely, the significantly opposite methylation and expression changes exemplified by LSP1, H19, TH, KCNQ1, SLC22A18, OSBPL5 are thus more likely random and unrelated to insulinoma pathogenesis." (PMID 33060578, 2020).
cancer (12 papers, 2019 to 2026). A tumor composed of atypical neoplastic, often pleomorphic cells that invade other tissues. "In addition, a previous study also showed that OSBPL5 interacts with the mammalian target of rapamycin (mTOR), and the PI3K/AKT/mTOR pathway is usually active in cancer." (PMID 34829830, 2021).
tumor (5 papers, 2019 to 2023). "We discovered that the protein levels of HNRNPK, P4HA1, and TUBA4A were significantly upregulated, while CTSL, HNRNPK, and OSBPL5 were significantly downregulated in the tumor tissues compared to those of normal tissues." (PMID 35284334, 2021). "However, the mRNA levels of CTSL, HNRNPK, LRIG1, and OSBPL5 were significantly downregulated in the tumor tissues compared to those observed in normal tissues." (PMID 35284334, 2021). "The results demonstrated that the protein expressions of OSBPL2 and OSBPL3 were elevated while OSBPL5, OSBPL6, OSBPL9, OSBPL10, and OSBPL11 were lowly expressed in tumor samples." (PMID 36918840, 2023). "As to the protein expression, OSBPL2 and OSBPL3 were significantly elevated and OSBPL5, OSBPL6, OSBPL9, OSBPL10, OSBPL11 were downregulated in tumor samples." (PMID 36918840, 2023). "The results displayed that the expressions of OSBPL3, OSBPL5, SOBPL7, and OSBPL10 were significantly correlated with tumor purity, B cell, CD8 + T cells, CD4 + T cells, macrophages, neutrophils, and dendritic cells infiltration levels." (PMID 36918840, 2023).
OSBPL5 also shares sentences with these, for which no sentence is quoted: pancreatic cancer (8 papers); alcohol dependence (3); Alzheimer disease (2); Anxiety (2); dementia (2); depression (2); encephalomyopathy (2); type 2 diabetes mellitus (2); breast carcinoma (1); cardiac hypertrophy (1); cholangiocarcinoma (1); cognitive deficits (1); colorectal cancer (1); infection (1); ischemic stroke (1); kidney cancer (1); lymph node metastasis (1); metastatic cancer (1); pancreatic adenocarcinoma (1); prostate tumors (1); renal cell carcinoma (1); transient cerebral ischemia (1).